XIST (X inactive specific transcript)
Diseases named in the same sentence as XIST in open-access papers (continued):
Sharing a sentence is not in itself a finding about the gene and the disease.
ovarian carcinoma (continued). "Overall, our findings suggest that ovarian cancer cells with XIST KD undergo EMT and are enriched with CSCs." (PMID 39546568, 2024). "Knockdown of XIST in ovarian cancer cell lines enhances cancer cell stemness and promotes the transition between cancer stem cell subtypes, particularly under hypoxic conditions." (PMID 39546568, 2024). "In this study, we explored the role of XIST (X-inactive specific transcript) long noncoding RNA in ovarian cancer stemness and plasticity through in silico and in vitro analyses." (PMID 39546568, 2024). "In particular, we showed that ovarian cancer cells with XIST KD were more likely to transdifferentiate into mesenchymal or epithelial CSC subtypes depending on their environment." (PMID 39546568, 2024). "In this study, we revealed the function of XIST lncRNA in ovarian cancer cell stemness and plasticity." (PMID 39546568, 2024). "To better understand the role of XIST in ovarian cancer cell stemness, we examined XIST expression in ovarian cancer cell lines through the CCLE (Cancer Cell Line Encyclopedia) database." (PMID 39546568, 2024). "Ovarian cancer cells with XIST KD also exhibit enhanced resistance to cell death under hypoxia, suggesting that XIST is involved in CSC maintenance and regulation." (PMID 39546568, 2024). "In both normoxia and hypoxia conditions, we observed an increase of the mesoderm index in sgXIST samples compared to sgCtl samples, suggesting that XIST KD enhances the mesodermal progenitor-like population in ovarian cancer cells." (PMID 39546568, 2024). "Knocking down XIST in ovarian cancer cells enhanced stemness, particularly increasing mesenchymal-like CSCs, and under hypoxic conditions, it promoted epithelial-like CSC markers." (PMID 39546568, 2024). "Our study here showed how a stable XIST KD in established cell lines affected the outcome of ovarian cancer cells." (PMID 39546568, 2024). "Here, we set out to investigate the expression of XIST lncRNA in ovarian tumors and elucidate its role in ovarian cancer cellular plasticity." (PMID 39546568, 2024). "In two independent ovarian cancer cell lines, knocking down XIST led to enrichment of the M-CSC subtype of CSCs." (PMID 39546568, 2024). "Our findings suggest that XIST loss leads to CSC enrichment and cellular plasticity in ovarian cancer, pointing to potential therapeutic targets for patients with low XIST expression." (PMID 39546568, 2024). "The relationship between XIST and autophagy has been reported in a variety of cells, such as hepatic stellate cells and ovarian cancer cells." (PMID 36908288, 2023). "In ovarian cancer, XIST was shown to regulate the miR-506-3p/FOXP1 axis, in turn regulating autophagy and carboplatin resistance." (PMID 36869839, 2023). "By contrast, downregulation of XIST was observed in ovarian cancer cells and tissues, and XIST suppressed ovarian cancer cell proliferation and inversely promoted cell apoptosis." (PMID 35899235, 2022). "We aimed to clarify the role of lncRNA X-inactive specific transcript (XIST)/miR-149-3p/forkhead box P3 (FOXP3) axis in ovarian cancer (OC) cell growth." (PMID 33542185, 2021). "For example, in ovarian cancer, the upregulation of lncRNA XIST has anticancer effects due to the inverse downregulation of has-miR-214-3p." (PMID 31384173, 2019). "XIST was reported to have key roles in many tumors including testicular germ cell tumors and ovarian cancer." (PMID 28388883, 2017). "XIST expression correlates with ovarian cancer cell sensitivity to taxol and high XIST levels are associated with late relapse." (PMID 27515027, 2016). "The effect of XIST on cellular plasticity may extend beyond breast and ovarian cancer to other cancer types." (PMID 39546568, 2024). "Such morphological phenotypes are typically associated with mesenchymal cells, suggesting the possibility that XIST KD might induce an epithelial-to-mesenchymal transition (EMT) in these ovarian cancer cells." (PMID 39546568, 2024).
ovarian carcinoma (continued). "Recently, in our laboratory, four aberrantly expressed lncRNAs (MEG3, POU5F1P5, ADAMTS9‐AS2, and XIST) were identified in ovarian cancer cell lines and primary ovarian surface epithelial cells and subsequently validated using multiple HGSCs and ovarian tissues." (PMID 38571514, 2024). "We performed XIST-KD in ovarian cancer cells using CRSPRi (CRISPR interference)." (PMID 39546568, 2024). "In both ovarian cancer cell lines, CRISPRi was effective in knocking down XIST expression." (PMID 39546568, 2024). "We found that cells with XIST KD were significantly enriched for M-CSC genes signature for both sgXIST7 (NES = 1.42) and sgXIST9 (NES = 1.27), validating increased mesenchymal-like cancer SC population in ovarian cancer cell with loss of XIST." (PMID 39546568, 2024). "The lncRNA XIST controls XCI (X chromosome inactivation) in all somatic cells, so we investigated whether XIST downregulation was associated with XCI regulation in ovarian cancer cells." (PMID 39546568, 2024). "However, further studies are needed to determine the regulatory mechanism of XIST expression in ovarian cancer." (PMID 39546568, 2024). "The results of this study suggest that the miR-93-5p/XIST/KMT2C signaling axis may provide new potential therapeutic targets for ovarian cancer treatment and play an important role in future ovarian cancer therapy." (PMID 39165358, 2024). "Furthermore, the oxidative phosphorylation pathway (OXPHOS), which is highly used by CSC, was enriched in OVCAR3-KRAB cells with XIST KD as well as in TCGA ovarian cancer patient samples." (PMID 39546568, 2024). "Moreover, sgXIST samples showed higher EB stemness index values than sgCtl samples under normoxia and hypoxia conditions, confirming that XIST KD enhances the population of CSCs in ovarian cancer cells." (PMID 39546568, 2024). "We observed an enrichment of M-CSCs after XIST KD in ovarian cancer cells." (PMID 39546568, 2024). "To determine whether XIST, JPX, and FTX downregulation could be caused by chromosomal deletions, we also examined Copy Number Variation (CNV) across ovarian cancer grades." (PMID 39546568, 2024). "We used flow cytometry to determine whether ovarian cancer cells with XIST KD exhibited the same mesenchymal-like SC characteristics with CD44high/CD24low as breast CSCs." (PMID 39546568, 2024). "lncRNA XIST was found to be upregulated in ovarian cancer and carboplatin-resistant cells." (PMID 36899946, 2023). "Moreover, the knockdown of XIST led to the suppression of proliferation and autophagy while inducing apoptosis in ovarian cancer cells." (PMID 36899946, 2023). "However, the expression of lncRNA XIST is lowered and miR-101 is upregulated in TAMs of breast and ovarian cancers, favoring M2 polarization-induced cell proliferation and migration of malignant cells." (PMID 36263199, 2022). "Interestingly, our analysis did not identify lncRNAs that had previously been reported to be associated with ovarian cancer, such as UCA1, HOTAIR, XIST, or H1913." (PMID 33499129, 2021). "Moreover, MALAT1, NEAT1, GAS5, H19 and XIST have been experimentally validated to be ovarian cancer-related lncRNAs, which were identified as hubs that connect 26, 15, 22, 20 and 9 modules in OV dataset, respectively." (PMID 30732558, 2019). "However, some other studies indicated that lncRNA XIST was lost in breast, cervical and ovarian cancer cell lines." (PMID 27620004, 2016). "While XIST expression levels are correlated with outcome in some cancers, such as the therapeutic response in ovarian cancer, the actual role that XIST may play in human carcinomas, if any, is not entirely clear." (PMID 21489289, 2011). "In human ovarian cancer cells, the correlation between X-linked DEGs and SINE density remained significantly positive after controlling for gene density, indicating a likely association between SINEs and transcriptional changes caused by XIST loss independently of gene-rich regions." (PMID 40981384, 2025).
ovarian carcinoma (continued). "In addition, XIST KD may increase CSCs in ovarian cancer cells based on our finding of a higher stemness index in ovarian tumors with low XIST expression." (PMID 39546568, 2024). "XIST, MEG3, IPW, HAND2‐AS, ADAMTS9‐AS2, and LINC00312 have been reported to be downregulated in ovarian cancers in several studies, which is consistent with the present study." (PMID 38571514, 2024). "In a hypoxic environment, however, XIST KD enhanced the E-CSC subtype of CSCs, thus improving survival of these ovarian cancer cells." (PMID 39546568, 2024). "While XIST has been thoroughly studied in the context of malignancy, HAND2-AS1’s role is relatively new in ovarian cancer, which prompted us to pursue investigations regarding this lncRNA." (PMID 32517089, 2020). "XIST and MEG3 have been reported to suppress cell migration and invasion in ovarian cancer." (PMID 38571514, 2024). "In our study, ovarian cancer cells with XIST KD exhibited enrichment of CSC under normoxia, and we further investigated whether XIST KD would increase CSC enrichment under hypoxia." (PMID 39546568, 2024). "Ovarian cancer SKOV3ip cells are known to be highly invasive and XIST KD did not significantly alter cell invasion or migration in SKOV3-KRAB; however, OVCAR3-KRAB cells with XIST KD exhibited increased invasion and migration." (PMID 39546568, 2024). "Hence, XIST competes with miR-101 to bind with C/EBPα and KLF6 and sponges miR-101 to upregulate the expression of C/EBPα and KLF6 in TAM of ovarian cancer and BC." (PMID 36263199, 2022). "Between human ovarian cancer cells and mammary cells, 16 upregulated and 8 downregulated DEGs were shared among the OVCAR3 KD X7 and X9, MaSC KO and ML KO samples; however, none of the shared DEGs were X-linked except for XIST itself." (PMID 40981384, 2025). "In addition, we found that X-linked DEGs associated with XIST loss were correlated with the density of transposable elements, LINEs but not SINES, in human ESCs; however, in human ovarian cancer and mammary cells, X-linked DEGs showed a higher correlation with SINEs than LINEs." (PMID 40981384, 2025).
hepatocellular carcinoma (31 papers, 2017 to 2024). A malignant tumor that arises from hepatocytes. "The results of the forest plot indicated that lower expression of XIST in the tumor tissues of patients with hepatocellular carcinoma or cervical squamous cell carcinoma was associated with shorter OS." (PMID 29568404, 2018). "The results of the forest plot demonstrated that hepatocellular carcinoma or esophageal squamous cell carcinoma patients with higher expression of XIST in the tumor tissues were associated with shorter DFS." (PMID 29568404, 2018). "Its dysregulation was found in several tumors (e.g., breast cancer, glioblastoma, and hepatocellular carcinoma), suggesting that XIST could have a potential diagnostic power in cancer." (PMID 29147648, 2017). "A more detailed mechanism of XIST is demonstrated in hepatocellular carcinoma, in which inhibiting XIST expression contributes to overexpression of miR-424-5p." (PMID 37178445, 2024). "Our study is one of the few studies on XIST expression in hepatocellular carcinoma that was conducted using tissue samples." (PMID 38265097, 2024). "Clinical characteristics of 82 hepatocellular carcinoma patients according to XIST expression levels." (PMID 38148658, 2023). "Here we reported a new regulated axis for HBV related hepatocellular carcinoma, namely, the lncRNA XIST-miR-192/TRIM25 axis." (PMID 33858324, 2021). "Upregulated lncRNA XIST in hepatocellular carcinoma was found, in another study, to activate AKT pathway through positive regulation of PDK1 expression via inhibiting miR-139-5p." (PMID 31998636, 2019). "XIST was reported to suppress cell proliferation, metastasis, invasion and exhibited tumor suppressive properties in hepatocellular carcinoma (HCC)." (PMID 31189404, 2019). "Meanwhile, XIST has been recently found to be down-regulated in hepatocellular carcinoma and cervical squamous cell carcinoma, and associated with the prognosis of these cancer patients." (PMID 29568404, 2018). "Among all included studies in this meta-analysis, two studies evaluated the expression level of lncRNA XIST and patient prognosis in hepatocellular carcinoma." (PMID 29568404, 2018). "One study reported that XIST expression was significantly down-regulated in hepatocellular carcinoma specimens in comparison with the adjacent normal tissues, while another study demonstrated XIST was upregulated in HCC tissues and cell lines." (PMID 29568404, 2018). "For instance, lncRNA XIST could regulate the progression of hepatocellular carcinoma via targeting miR-497-5p to regulate the expression of PDCD4." (PMID 33663502, 2021). "Another well-studied lncRNA, X-inactive specific transcript (XIST), could directly interact with miR-92b and repress each other, besides, XIST could inhibit hepatocellular carcinoma cell proliferation and metastasis." (PMID 29383134, 2017). "Mediated by XIST, miR-92b-3p could accelerate tumor progression in hepatocellular carcinoma." (PMID 36312586, 2022). "Recent study has shown that exosomal JPX from hepatocellular carcinoma (HCC) cells promotes XIST expression by inhibiting the function of CCCTC-binding factor (CTCF) in blood cells." (PMID 31941509, 2020). "In hepatocellular carcinoma, JPX-dependent induction of XIST suppresses hepatocellular carcinoma progression by binding to the miR-155-5p oncomiR." (PMID 33261009, 2020). "XIST was shown to exhibit tumor suppressive properties in hepatocellular carcinoma (HCC) by acting as a miRNA decoy for tumor suppressor genes, SMAD7 (SMAD family member 7) and PTEN, by sponging miR-92b and miR-181a, respectively, and suppressing cell proliferation, metastasis, and invasion." (PMID 29702599, 2018). "An oncogenic role of XIST has been coherently indicated for other tumors, such as laryngeal squamous cell carcinoma, esophageal cancer and osteosarcoma, whereas contrasting results have been published for hepatocellular carcinoma (HCC), where a tumor suppressor role has mainly been attributed." (PMID 35054794, 2022).
hepatocellular carcinoma (continued). "However, XIST is abnormally expressed in various cancers, including hepatocellular carcinoma (HCC)." (PMID 34295808, 2021).
bladder cancer (25 papers, 2018 to 2025). "Our study revealed that XIST expression is significantly higher in female bladder cancer tissues and strongly associated with poor prognosis in female patients." (PMID 40308577, 2025). "Beyond LINC01094, other lncRNAs—including MALAT1, UCA1, and XIST, among others—have also been implicated in bladder cancer progression or metabolic reprogramming." (PMID 40438104, 2025). "Our data indicate that FZD2 promotes bladder cancer cell proliferation and migration, and that the regulation of these functions by XIST is closely linked to FZD2." (PMID 40308577, 2025). "Based on the results from our study investigating the underlying mechanism of XIST and miR-200c in regulating bladder cancer cell growth and invasion, XIST might be considered as a potential target for suppressing the proliferation, metastasis and tumourigenicity of human BCSCs." (PMID 29559853, 2018). "We discovered that the XIST/miR-15a-5p/MN1/FZD2 signaling axis plays a significant role in regulating the progression of bladder cancer." (PMID 40308577, 2025). "The XIST/miR-15a-5p/MN1/FZD2 signaling axis was found to play a critical role in promoting bladder cancer progression." (PMID 40308577, 2025). "Rescue experiments showed that XIST influences the biological functions of bladder cancer cells by regulating MN1 expression." (PMID 40308577, 2025). "The XIST/miR-15a-5p/MN1 signaling axis plays a critical role in the gender disparity observed in bladder cancer prognosis, particularly in women." (PMID 40308577, 2025). "To evaluate the expression of the XIST gene in bladder cancer (BC) cells, we assessed XIST expression in SV-HUC-1 (normal bladder epithelial cells), RT4 (male BC-derived), and T24 (female BC-derived) cells." (PMID 40308577, 2025). "In this study, we identified the critical role of the XIST/miR-15a-5p/MN1/FZD2 signaling axis in explaining gender disparities in bladder cancer prognosis." (PMID 40308577, 2025). "Our findings show that the upregulation of XIST significantly correlates with poorer prognosis in female bladder cancer patients, pointing to its potential as a novel therapeutic target." (PMID 40308577, 2025). "To further elucidate the molecular mechanisms by which the XIST gene influences bladder cancer cell functions, we performed RNA sequencing analysis on T24 cells." (PMID 40308577, 2025). "Several studies have reported that XIST expression is upregulated in bladder cancer tissues and functions as an oncogenic gene in cancer development." (PMID 36605618, 2023). "Studies have demonstrated that PD reduced the expression of XIST and inhibited the growth of bladder cancer cells." (PMID 36035993, 2022). "Knockdown of XIST significantly suppresses cell proliferation and migration and induces apoptosis in bladder cancer cells, whereas overexpression of XIST has the opposite effects." (PMID 35269796, 2022). "XIST silencing has decreased proliferation, invasion, and migratory potential of bladder cancer through modulation of AR signaling." (PMID 34831421, 2021). "A knock down of XIST showed a decrease in AR protein expression and repressed cell proliferation; this means that XIST regulates AR expression, and both function as oncogenes in bladder cancer." (PMID 33919565, 2021). "Another study has indicated parallel over-expressions of XIST and androgen receptor (AR) in bladder cancer cells." (PMID 34179019, 2021).